IL6 (interleukin 6)
Diseases named in the same sentence as IL6 in open-access papers (continued):
Sharing a sentence is not in itself a finding about the gene and the disease.
infection (continued). "IL-6 levels increase 2 h after infection, peak 4 h after infection, and return to normal 8 h after infection due to its half-life of 100 min." (PMID 39886481, 2025). "IL-6 is a pleiotropic immunomodulator that promotes host defense by stimulating acute-phase responses, hematopoiesis, and immune responses in response to infection and tissue injury." (PMID 40365536, 2025). "The human body initiates an inflammatory response in reaction to injury or infection, which triggers the production of IL-1, IL-6, IL-8, TNF-α, and other inflammatory factors by white blood cells." (PMID 41142623, 2025). "Activated innate cells phagocytose Candida and release pro-inflammatory cytokines (IL-1, TNF-α, IL-6) that help recruit more immune cells to the site of infection." (PMID 40586608, 2025). "IL-6, as the main pro-inflammatory cytokine, can be produced immediately and contributes to host defense against infection by stimulating specific cellular and humoral immune responses." (PMID 40784366, 2025). "Serum protein levels of IL-1β (B), TNF-α (C), and IL-6 (D) were examined through ELISA assays 24 hr post infection." (PMID 39998486, 2025). "Among patients with positive blood cultures, only IL-6 showed significant elevation, highlighting its value in early infection recognition." (PMID 41293058, 2025). "Changes in IL-6 levels were detected in IPEC-J2 cells 6 h after infection with EHEC or S. flexneri (p < 0.001 in each case) or EPEC (p = 0.0225) at 5 × 107 CFU/mL compared to non-infected counterparts." (PMID 40426498, 2025). "The proportion of LTA+/LPS+ EVs in plasma increased with prolonged infection time, aligning with the temporal patterns of early inflammatory markers IL‐6 and CRP." (PMID 40903799, 2025). "HCoV-229E induced both IFN-β and IFN-λ transcription in infected Huh7 cells but only at a late stage during infection, and a similar observation was made for the NF-κB-regulated IL-6 gene." (PMID 39940968, 2025). "In the pig ASFV trial, levels of pro-inflammatory cytokines, including IL-6 and IL-8 increased from 3 days p.i., while IL-10 was only detected at the terminal stages of the infection together with a second peak in pro-inflammatory cytokine levels." (PMID 40533814, 2025). "The majority of the pro-inflammatory cytokines were upregulated after 7 days post infection, except IL-6, which was found to be more pronounced at 14 days than at 7 days post infection indicating active H. pylori infection." (PMID 38602383, 2025). "The results demonstrated an increase in IκBα degradation as well as an increased phosphorylation of IκBα during infection in LRSAM1-deficient cells, indicating an elevated activity of the NFκB-pathway with increased secretion of IL-6 upon infection." (PMID 40861495, 2025). "Neutralization of TGF-β throughout infection dramatically increased cellular infiltration in all lung spaces at 3 dpi and increased systemic IL-6 and IL-22." (PMID 40854598, 2025). "Pleural interleukin-6 levels in infection were 5000-fold higher than matched serum levels (median 72,752 pg/ml vs. 15 pg/ml)." (PMID 40819633, 2025). "The infection factor had a significanteffect on the Il6 expression in the frontal cortex, andthis outcome contributed to an increase in the parameter inEth+OF mice to the control level; this parameter was lowerin Eth mice than in OF mice." (PMID 40144377, 2025). "Despite partial IgG induction upon repeated dosing, PEGylated phages maintained superior PK and significantly suppressed infection-driven IL-6, IFN-γ, TNF-α, and IL-1β, normalizing cytokine profiles toward baseline." (PMID 41309396, 2025). "IL6 also enhances B-cell differentiation, antibody secretion, and immune defense, aiding pathogen clearance and reducing infection-induced inflammation and oxidative stress." (PMID 41153906, 2025).
infection (continued). "After the infection, RNA was extracted and reverse transcribed, and the transcription of pro-inflammatory factors IL-6, IL-8, and Tumor Necrosis Factor-α (TNF-α) was detected with reverse transcript polymerase chain reaction (RT-PCR)." (PMID 40332097, 2025). "At 35 days after infection, during the chronic phase, we observed an increase in the Th2 cytokines IL-6 and IL-10 in infected mice." (PMID 39899646, 2025). "ELISA further showed dose-dependent reductions in the release of key inflammatory mediators: interferon-β (IFN-β), tumor necrosis factor-α (TNF-α), and interleukin-6 (IL-6), all of which were significantly different (all p < 0.05) from those in WT infection." (PMID 41301507, 2025). "Latent infection with T. gondii affects signalling pathways in the brain and induces IL-6 neurotoxic effects." (PMID 41018675, 2025). "The inserts infected with JN.1 showed a peak of IL-6 on day 2 post-infection, with significance compared to day 0 (p = 0.0090), day 1 (p = 0.0489), day 3 (p = 0.0084), and day 4 (p = 0.0161)." (PMID 40733536, 2025). "In mouse sera post-PCV2 infection also showed elevated levels of IL-6, IL-8 IL-10, TNF-α, and MCP-1 (p < 0.05 or p < 0.01)." (PMID 39968105, 2025). "M. abscessus coinfection was able to inhibit the higher production that was reported in P. aeruginosa single-infected cells, and the release of IL-6 and IL-8 was reduced to levels similar to those triggered by M. abscessus single infection." (PMID 40237819, 2025). "Regulation of ZIP14 expression by inflammatory cytokines like IL-6 couples increases in iron uptake to infection and chronic inflammation." (PMID 41007630, 2025). "The production of key cytokines (IL‐1β, IL‐18, IL‐6, IL‐10, IL‐12) and nitric oxide (NO) was quantified at 24 to 96 h post‐infection." (PMID 40940710, 2025). "After infection, the expression levels of Il10, Tnfa, Il1b and Il6 increased significantly in both young and aged mice at 4 dpi, peaking at 7 dpi." (PMID 41145556, 2025). "Compared to the control group, the protein expressions of TNF-α, IL-1β, and IL-6 in the GPS infection group were significantly higher (p < 0.01)." (PMID 40867785, 2025). "The IL-6/STAT3 pathway plays a significant role in regulating the immune response during these infections, particularly by modulating cytokine production, inflammatory cell recruitment, and acute-phase responses." (PMID 41137299, 2025). "In our study, in women with PCOS and confirmed infection with any atypical pathogen (n = 196), we analyzed the levels of proinflammatory cytokines, such as IL-1β, IL-6 and TNF-α, which are important in this type of infection." (PMID 40647668, 2025). "Interleukin-6 (IL-6), produced by monocytes, macrophages, and endothelial cells in response to infection, plays a key role in this inflammatory process." (PMID 41012595, 2025). "IHC staining revealed that intraperitoneal arginine administration suppressed infection-induced upregulation of proinflammatory cytokines IL-6 and TNF-α." (PMID 41181117, 2025). "IL-6 promotes the increase of IgM, IgG, and IgA and stimulates T helper cell proliferation during inflammation or infection." (PMID 40149646, 2025). "Specifically, infected mice exhibited a notable increase in proinflammatory cytokines, including MCP-1, IFN-γ, IL-12p70, TNF-α, and IL-6, particularly at 10 days post-infection (dpi)." (PMID 40078875, 2025). "We noted the increased expression of Il1b, iNos, Ifng in the case of H1N1wsn, and Il6 in the case of H1N1pdm09 infection." (PMID 41567998, 2025). "As the optimal set of predictors for postoperative infection risk assessment still has to be investigated, we cannot conclude yet on the superiority of either IL-6 or CRP when used in combination with such a set of predictors for postoperative infection." (PMID 40549692, 2025). "We observed similar results regarding infection, although further exploration of predictive performance measures in a multivariable approach suggested limited clinical relevance of IL-6." (PMID 40549692, 2025).
infection (continued). "In TB, NAC limits infection by modulating host oxidative responses and inhibiting IL-6 production via MAPK/NF-κB signaling." (PMID 40575568, 2025). "Macrophages derived from STS mice produced higher levels of several soluble factors, including CCL5/RANTES, G-CSF, TNF alpha, and IL-6, than macrophages from CcS-11 mice even before infection." (PMID 39875898, 2025). "Its expression increases through the mediation of various cytokines, especially IL-6, as a response to inflammation and infection." (PMID 40629656, 2025). "Neutrophils release proinflammatory cytokines (such as IL-6 and TNF-α), which can potentially damage lung epithelial integrity and exacerbate the risk of infection." (PMID 40270508, 2025). "Both strains augmented IL-27 (6 h) and only L. plantarum MPL16 increased IL-6 and IL-8 at 6 h post-infection." (PMID 41155369, 2025). "CRP is a classical acute-phase reactant synthesized by hepatocytes in response to cytokines such as IL-6 and increases in conditions like infection and sepsis." (PMID 40941711, 2025). "During ECMO, the levels of IL6, an inflammatory marker, can be influenced by several factors, including infection, tissue injury, and the patient's baseline health status." (PMID 39863122, 2025). "Clinical variables associated with an adverse outcome included age, admission GCS, Rotterdam score, hospital-acquired infection, and IL-6 levels on admission." (PMID 40713822, 2025). "One of these cytokines is interleukin-6 (IL-6), which acts as a pyrogen and plays an important role in the immune response during inflammation and infection." (PMID 41012647, 2025). "In SCAT of aged mice, infection induced an increase in Il10 levels at 4 and 7 dpi, Tnfa at 4 dpi, and both Il1b and Il6 at 7 dpi." (PMID 41145556, 2025). "We additionally show that atRA correlates with some inflammatory cytokines across infection types, including IL‐1β, IL‐6, IL‐10 and IL‐12." (PMID 40031928, 2025). "This study was designed with catheter functional duration and IL-6 levels as the primary endpoints, while infection, thrombosis, and additional inflammatory markers were predefined as secondary, exploratory outcomes." (PMID 41254792, 2025). "We found higher IL-1b levels in adult serum and PBMC cultures post-infection, correlating with age and promoting IL-6, IL-9, and IL-17A secretion when combined with IFNa." (PMID 40834853, 2025). "We found that infection with all strains of Ot upregulated the expression of IL-6, TNF-alpha, IL-1ß, and CXCL-10 (human macrophages only) both in the presence and absence of IFN-γ." (PMID 40587585, 2025). "Significant increases in plasma IL-6 levels during infection reflect a robust innate immune reaction to viral intrusion, consistent with previous findings." (PMID 40407816, 2025). "IL-6 is a potent inducer of the acute phase response, and thus plays an important role in the initial phase of an infection." (PMID 40372987, 2025). "Here, we found significantly higher expression of the pro-inflammatory cytokines IL-6 and TNF-α in response to ST infection in cell culture supernatants of Nedd9-deficient mBMDMs measured by ELISA." (PMID 40506423, 2025). "Cytokine induction in a human neutrophil model showed significantly increased IL-6 expression following infection with the beta-hemolysin producing strain (ΔΦ13)." (PMID 40900037, 2025). "We compared TOA regimens (full, pre, co, post), evaluated combinations with nirmatrelvir (NL63) or GS-441524 (OC43) using ZIP scores, and profiled infection-context transcripts (IL6, IFNB1, ISG15, NRF2/antioxidant, UPR)." (PMID 41304814, 2025). "In vivo, arbutin inhibited the systemic inflammatory response induced by Tg infection, as evidenced by reduced serum levels of IFN-γ, CCL2/MCP-1, and IL-6 four days post-infection." (PMID 41379884, 2025). "The IL-6 concentration in the serum of the mice after 24 h of infection was measured to assess the severity of the infection." (PMID 40006601, 2025).
infection (continued). "In the presence of SA infection for 10 h, KCs exhibited an expected pro-inflammatory M1 phenotype, with significant increases in expression of Il6, Tnf, and Nos2 (L2FC = 5.72, 7.13, and 4.16, respectively; P < 0.0001)." (PMID 41025812, 2025). "It suppresses the production and release of TNF-α and IL-6 in macrophages induced by H. pylori, thereby controlling infection-related inflammatory responses and preventing pathological changes." (PMID 40831563, 2025). "Protein abundance of TNF-α, IL-1β, and IL-6 increased at 24 h after infection, consistent with mRNA abundance." (PMID 40663568, 2025). "We show an inverse correlation between the decrease in atRA and the increase in inflammatory cytokines IL‐1β, IL‐6, IL‐10 and IL‐12 in lung tissue during infection." (PMID 40031928, 2025). "In parallel, proinflammatory cytokines (IL-1β, TNF-α, IL-6, IFN-α, and IFN-β) were measured, only IL-6 was significantly increased following SUCNR1 knockdown upon infection." (PMID 41492386, 2025). "This study delineated the spatiotemporal dynamics of SAA, IL-1β, and IL-6 gene expression during Ich infection." (PMID 40509043, 2025). "Candidates include procalcitonin (PCT), interleukin-6 (IL-6), and other cytokines or acute-phase reactants that rise in infection." (PMID 41153812, 2025). "Proinflammatory cytokines, such as TNFα, IL-1β, and IL-6, produced after pathogen infection or tissue damage, contribute to mounting an effective immune response." (PMID 40462232, 2025). "By 24 h post-infection, IL-6 levels rose significantly across all infection phases compared to the control, with rNRP1-infected explants exhibiting the highest expression of this cytokine." (PMID 41450943, 2025). "The concentration of chemokines CxCL1/KC/GRO-α, CxCL2/MIP-2, CCL5/RANTES and cytokines TNF-α, IL-1β, IFN-γ, IL-5, IL-6, IL-9, IL-10, IL-13, IL-17, IL-23 circulating in blood were measured in experimental animals on day 15 post-infection." (PMID 40445994, 2025). "In Mendelian randomisation analyses, interleukin-6 inhibition was predicted to have a large protective effect on the incidence of infection (OR 0.23; 95% CI 0.14–0.39 per standard deviation decrease in C- reactive protein)." (PMID 40819633, 2025). "The increased levels of TNF-α, IL-1β, and IL-6 promote endothelial activation and leukocyte recruitment to the site of infection, which plays a crucial role in the host’s innate immune defense." (PMID 40564979, 2025). "Laboratory evaluations, including complete blood count (CBC), high-sensitivity C-reactive protein (hs-CRP), and interleukin-6 (IL-6), were performed at baseline, 1 month, and 6 months, or upon clinical suspicion of infection." (PMID 41254792, 2025). "The inflammatory response triggered by PAO1 and PAET1 single infections in epithelial cells clearly exacerbated the production of the proinflammatory cytokines IL-6 and IL-8." (PMID 40237819, 2025). "In response to the infection, immune cells produce pro-inflammatory cytokines such as interleukin (IL)-1, IL-6, and tumor necrosis factor (TNF)-α, which disrupt homeostasis." (PMID 39941433, 2025). "ACE2-Fc additionally reduces cytotoxicity following infection with different virus strains and inhibits the post-infection release of IL-6 and TNF-α from PBMCs." (PMID 40571942, 2025). "The correlation between SARS-CoV-2 and IL-6 levels requires further clarification, as it reflects different stages or contexts of infection." (PMID 39940645, 2025). "Maximum IL-6 and CRP concentrations within 24 hours from the start of surgery were associated with postoperative infection." (PMID 40549692, 2025). "Influenza virus infection can induce DCs to produce inflammatory factors such as TNF-α and IL-6, which play a role in regulating the inflammatory response and attracting other immune cells to the infection site." (PMID 40872644, 2025).
infection (continued). "Assessing the differences in expression of the target genes between the time points, significant differences in expression were only observed for il1b and il6 between 6 and 18 h post infection for both treatments." (PMID 40517265, 2025). "C57BL/6 mice infected with Helicobacter pylori (H. pylori) develop SPEM six months after infection, accompanied by increased expression of IL-6 and p-STAT311." (PMID 40520011, 2025). "This activation is followed by an induction and secretion of pro-inflammatory cytokines like IL-6, which mediates the recruitment of innate immune cells like neutrophils and macrophages to the site of infection." (PMID 40861495, 2025). "Previous studies have revealed that K. pneumoniae is capable of inducing a pro-inflammatory cytokine response in BMECs, as evidenced by the release of cytokines such as TNF-α, IL-1β, and IL-6, consistent with our results in a model of BMECs infection." (PMID 41206543, 2025). "Several studies have shown that TLR2 and TLR4 recognize components of the fungal wall and contribute to the production of proinflammatory cytokines, such as TNF-α, IL-6, and IL-1β, which promote the recruitment of immune cells to the infection site." (PMID 41590416, 2025). "Accordingly, the eosinophil-activating cytokine IL-5 was elevated in the intestinal samples out to 15 days post-infection, although other inflammatory cytokines investigated (e.g., IL-1β, IL-6, TNF) were unchanged." (PMID 39861887, 2025). "The combination of TA:SeCA coated catheter segments with GSNO and GSH resulted in substantial reductions in key pro‐inflammatory cytokines, TNF‐α and IL‐6, highlighting its potential to mitigate inflammation, infection, and thrombosis." (PMID 40879081, 2025). "IL-8 plays a key role in recruiting neutrophils and other immune cells to the site of infection; IL-8 and IL-6 detection together can be used as a predictor for disease severity in patients." (PMID 40295859, 2025). "Currently, literature considering IL-6 as a predictor for postoperative infection in pulmonary surgery is scarce." (PMID 40549692, 2025). "To address this, we analyzed the transcriptional expression of the cytokines Il-6, Tnf, and the chemokine Ccl5/Rantes throughout the course of infection in the brain." (PMID 41362627, 2025). "IL-6 contributes to antiviral immunity by promoting the recruitment of immune cells to sites of infection and amplifying the inflammatory response." (PMID 40692679, 2025). "Exceptions to this were IL1α, which favored the apical compartment, and IL-6, which changed from being expressed in both compartments to basolateral during late infection (6 dpi)." (PMID 41157615, 2025). "New evidence indicates that biomarkers such as cortisol, IL-6, glucose, and albumin serve as predictors of postoperative complications, including infection, impaired wound healing, and increased morbidity." (PMID 41589142, 2025). "High-dose infection with all the strains elicited significant increases in GM-CSF, IL-1β, IL-2, IL-4, IL-5, IL-6, and IL-12p70 when compared with the PBS control." (PMID 40333117, 2025). "As 20% of the participants reported resolution of symptoms 4–12 weeks after infection, the trends of IL–1β, IL–6, and TNF levels in these patients over time were also assessed." (PMID 40217938, 2025). "For example, IL-6, as a key regulator of the inflammatory response, can rapidly activate various signaling pathways during stress states such as infection and trauma." (PMID 40218314, 2025). "For this reason, the expression of the pro-inflammatory cytokines IL-1β, IL-6, and IL-8 and hBDs was analyzed in oral epithelial cells following infection with C. albicans." (PMID 40426561, 2025). "The salivary concentration of IL-6, which is a multifunctional proinflammatory cytokine synthesized in response to tissue damage and infection, was determined." (PMID 40002575, 2025).